PCSK9 (proprotein convertase subtilisin/kexin type 9)
Diseases named in the same sentence as PCSK9 in open-access papers (continued):
Sharing a sentence is not in itself a finding about the gene and the disease.
cardiovascular disease (continued). "Since proprotein convertase subtilisin kexin 9 (PCSK9) discovery, a gene involved in LDL metabolism regulation and cardiovascular diseases (CVD), many therapeutic strategies have been introduced for direct targeting of PCSK9." (PMID 29230236, 2017). "Proprotein convertase subtilisin/kexin type 9 (PCSK9) is a novel biomarker of LDL clearance and a therapeutic target of cardiovascular disease." (PMID 23862065, 2013). "Proprotein convertase subtilisin/kexin type 9 (PCSK9) inhibitors offer clinical benefits by reducing low-density lipoprotein cholesterol levels and have emerged as valuable therapeutic agents for the management of cardiovascular diseases." (PMID 41247317, 2025). "This multifaceted role suggests that PCSK9 is not merely a cholesterol regulator but also a key player in the inflammation-driven mechanisms of cardiovascular disease." (PMID 40354375, 2025). "In summary, PCSK9 inhibitors represent a novel class of pharmacological agents that has revolutionized and dramatically changed the landscape in treating elevated LDL cholesterol and cardiovascular diseases." (PMID 39479289, 2024). "A previous study reported recommendations from several guidelines on approaches to PCSK9 inhibitors in primary prevention of cardiovascular disease with a consideration of diabetic and nondiabetic patients." (PMID 36935878, 2023). "Many studies have shown an important role of PCSK9 in the pathogenesis of cardiovascular diseases, partly independent of its effect on lipid metabolism." (PMID 36831039, 2023). "Use of the proprotein convertase subtilisin-kexin type 9 (PCSK9) inhibitor evolocumab reduces low-density lipoprotein (LDL) cholesterol by ~60% and lowers the rate of cardiovascular events among patients with established cardiovascular disease." (PMID 35404972, 2022). "Numerous studies have shown that PCSK9 plays a significant role in cardiovascular disease, partially independent of its effect on lipid metabolism, and modern lipid-lowering therapy can help reduce cardiovascular risk in adults." (PMID 35566668, 2022). "Moreover, recent studies have reported the other functions of PCSK9 in cardiovascular events, independently of LDL-cholesterol regulation, including its role in promoting platelet activation and coagulation during cardiovascular disease progression." (PMID 35207479, 2022). "Monoclonal antibodies and/or antisense therapy directed against PCSK9 and ANGPTL3 are FDA approved in other indications than cancers (cardiovascular disease, familial hypercholesterolemia), while inhibitors of Lp(a) are currently investigated in clinical trials (ex: Phase 3 trial NCT04023552)." (PMID 36203122, 2022). "Diminished expression of PCSK9 resulted in periportally elevated LDL-receptor contents and significantly reduced volume of the free LDL, which effectively prevented the occurrence of cardiovascular diseases." (PMID 35414791, 2022). "Recently, in the first randomized controlled study, evolocumab, proprotein convertase subtilisin-kexin type 9 (PCSK9) inhibitor, has significantly improved the recurrence of cardiovascular disease but without significant difference in all-cause mortality." (PMID 35215263, 2022). "Gain of function (GOF) PCSK9 mutations were identified as the third genetic cause of autosomal dominant FH and an increasing attention has been drawn to targeting PCSK9 for the reduction of LDL-C levels and the prevention of cholesterol-driven cardiovascular disease." (PMID 35454151, 2022). "Finally, PCSK9 positively correlates with white blood cells (WBC) and in particular with neutrophils, markers of cardiovascular disease." (PMID 35071356, 2021). "Genetic and interventional clinical studies with PCSK9 monoclonal antibodies have demonstrated that PCSK9 inhibition efficiently reduces plasma LDL cholesterol and represent an efficient and safe strategy to protect against cardiovascular diseases." (PMID 34280453, 2021).
cardiovascular disease (continued). "The poster child for a success story of genetically driven drug discovery and development is without doubt the development of proprotein convertase subtilisin kexin type 9 (PCSK9) inhibitors in cardiovascular diseases." (PMID 31379482, 2019). "Statin therapy and the PCSK9 inhibitor evolocumab have been shown to lower LDL cholesterol levels and to reduce the rate of cardiovascular events among patients with established cardiovascular disease." (PMID 31437157, 2019). "Among these studies, adults with Lp(a) level more than 150 mmol/l or patients with LDL-C more than 100 mg/dl in the absence of cardiovascular diseases were deemed eligible to be included, while the usage of any monoclonal antibody drug targeting PCSK9 was considered as an exclusion criterion." (PMID 40338464, 2025). "Although advances in the understandings of genetic PCSK9 polymorphisms have enabled to reveal the role of PCSK9 in the complex pathophysiology of cardiovascular diseases (CVDs), increasing lines of evidence support non-cholesterol-related processes mediated by PCSK9." (PMID 37378405, 2023). "With the introduction of proprotein convertase subtilisin/kexin type 9 (PCSK9) inhibitors, sodium-glucose cotransporters-2 (SGLT2) inhibitors, and glucagon-like peptide-1 receptor (GLP-1) agonists more treatment options are becoming available for patients with cardiovascular disease." (PMID 35986769, 2022). "Blockage of PCSK9 lowers serum LDL and may protect from cardiovascular diseases." (PMID 33920491, 2021). "If so, then activation of LCAT by a small molecule approach and improving HDL function could be widely used in the primary prevention of cardiovascular disease and would likely complement our existing drugs for lowering LDL-C, such as statins and PCSK9-inhibitors." (PMID 30479275, 2018). "In addition, these current factorial clinical trials regarding cardiovascular disease mainly focused on statin but not proprotein convertase subtilisin/kexin type 9 (PCSK9) inhibitors for lipid lowering, and β-blockers (BBs) for antihypertension were rarely studied." (PMID 38764043, 2024).
cancer (168 papers, 2013 to 2026). A tumor composed of atypical neoplastic, often pleomorphic cells that invade other tissues. "Our findings in TNBC align with some of the prior studies indicating that increased PCSK9 expression is associated with increased tumor growth and metastasis in other types of cancers." (PMID 40192514, 2025). "Beyond its canonical role in cholesterol metabolism, PCSK9 has been implicated in various aspects of hepatic pathophysiology, including lipid metabolism, inflammation, cellular migration, and cancer progression." (PMID 40764605, 2025). "Emerging evidence indicates that PCSK9 exhibits aberrant expression in various cancers and is closely associated with patient prognosis." (PMID 40328788, 2025). "Emerging data suggest a link between PCSK9 and cancer: PCSK9 gain-of-function variants are associated with higher LDL-C and an increased risk of BC, while loss-of-function variants show the opposite effect." (PMID 39796190, 2025). "We employed cis-Mendelian randomization and colocalization to evaluate the role of 5 lipid-perturbing drug targets (ANGPTL3, ANGPTL4, APOC3, CETP, and PCSK9) in risk of 5 cancers (breast, colorectal, head and neck, ovarian, and prostate)." (PMID 40511612, 2025). "In summary, we demonstrated the causal relationship between gene-mediated PCSK9 inhibitors and malignant tumors through comprehensive dual-sample MR analysis, emphasizing the model of causal relationship between the immune system and malignant tumors." (PMID 38275613, 2024). "This review also highlights PCSK9’s aberrant expression in various cancer forms, its association with cancer prognosis, and its crucial roles in carcinogenesis and cancer immunity." (PMID 38185721, 2024). "Through the analysis of genome-wide association studies (GWAS), this study probed the causal link between PCSK9 inhibitors and cancer." (PMID 38275613, 2024). "Specifically, PCSK9 has been implicated in promoting EMT via activating Snail 1 in cancer cells, contributing to tumor progression and metastasis." (PMID 39722825, 2024). "In order to further examine aberrant patterns and the possible clinical importance of PCSK9 across various cancer types, a survival association study was carried out." (PMID 37860186, 2023). "Regarding PCSK9 (Proprotein convertase subtilisin/kexin type 9), previous studies described an association among PCSK9 overexpression and incidence and progression of different cancers but EC." (PMID 36745330, 2023). "We demonstrate applicability to ex vivo knock-in of a cancer-directed transgenic T cell receptor in primary human T cells and in vivo adenovirus knock-out of cardiovascular risk gene PCSK9 in mice." (PMID 37024653, 2023). "To determine the genomic mutations of PCSK9 in tumors, we reviewed the genetic alterations of the PCSK9 gene in cancer patients using the cBioPortal database." (PMID 37860186, 2023). "In the current study, we thoroughly examined the relationships among PCSK9 expression, methylation, mutation, and patient prognosis in 33 different cancer types." (PMID 37860186, 2023). "Overall, the pan-cancer survival analysis revealed an association between dysregulated PCSK9 and poor clinical outcomes in various cancer types." (PMID 37860186, 2023). "Taken together, aberrantly expressed PCSK9 was related to cancer progression and cancer prognosis through modulation of PCSK9 DNA methylation, an epigenetic hallmark of cancer." (PMID 37860186, 2023). "The risk of new and worsening cancer events was assessed among participants who received the proprotein convertase subtilisin/kexin type 9 inhibitor alirocumab combined with a statin." (PMID 37458138, 2023). "Pan-cancer analysis of TCGA data showed that PCSK9 is highly expressed in various cancers and is associated with poor prognosis." (PMID 37151886, 2023).
cancer (continued). "In this context, data from recent meta-analysis and cardiovascular outcome trials associate PCSK9 levels to reduced ICIs-related cancer responsiveness and to high risk of atherosclerotic cardiovascular diseases." (PMID 36900189, 2023). "CD8+ T cells, DCs, and M2 macrophages were the immune cell subtypes most positively associated with PCSK9 expression in these different cancers." (PMID 37860186, 2023). "Since the expression of PCSK9 is sex-related, research is needed to explore if there are differences in the association of PCSK9 and cancer risk between men and women." (PMID 37860186, 2023). "Assess the risk of new and worsening cancer events among participants who received the lipid‐lowering therapy alirocumab, a proprotein convertase subtilisin/kexin type 9 inhibitor." (PMID 37458138, 2023). "What is more, the combination of PCSK9 inhibitors and ICIs therapy was found to enhance the outcome of malignant tumors, which suggests that there is an underlying association between PCSK9 level and efficacy of ICI therapy." (PMID 34962050, 2022). "PCSK9 is now attracting more attention in oncology because its tight association with the incidence and progression of several cancers." (PMID 36612001, 2022). "Combined with the present results, these studies support the need to confirm the association, if any, between PCSK9 elevation and enhanced cancer aggressivity." (PMID 36203122, 2022). "Cancer risk analysis of subjects carrying loss-of-function and gain-of-function mutations in PCSK9 will further reveal and confirm the role of PCSK9 in cancer progression." (PMID 34782856, 2021). "The decreased expression can be attributed to mutations in PCSK-9 as well as deregulations in cancer signaling pathways (e.g., NF-κβ) that facilitate cholesterol accumulation through decreased PCSK-9 expression." (PMID 34869315, 2021). "As indicated by the univariate COX regression model, Lauren’s classification, Tumor Differentiation, T staging, N staging, M staging, TNM staging, and PCSK9 expression were significantly associated with an increased risk of cancer-related death." (PMID 33489919, 2020). "In oncology, PCSK9 inhibition has been linked to improved immune surveillance and potential tumor-suppressive effects, making inclisiran an attractive candidate for adjunctive therapy in cancer patients." (PMID 40724868, 2025). "Several studies indicate that PCSK9 is associated with the initiation of cancer progression." (PMID 40145543, 2025). "Its dual role-associating with improved survival in some cancers while correlating with worse outcomes in others-suggests that PCSK9 may influence cancer progression through context-dependent mechanisms." (PMID 40576911, 2025). "We employed drug-target Mendelian randomization (MR) to systematically evaluate the effect of 5 approved or emerging lipid-perturbing drug targets for CVD (APOC3, ANGPTL3, ANGPTL4, CETP, and PCSK9) on risk of 5 cancers (breast, colorectal, head and neck, ovarian, and prostate)." (PMID 40511612, 2025). "Despite these promising findings, further clinical trials are needed to determine whether PCSK9 inhibitors confer a direct protective effect against cancer and better understand the underlying mechanisms involved in their potential anticancer properties." (PMID 40364115, 2025). "Nonetheless, our findings suggesting little evidence of association of genetically proxied ANGPTL3, APOC3, CETP, and PCSK9 inhibition with cancer risk may help to deprioritize further evaluation of these proteins as intervention targets for cancer prevention." (PMID 40511612, 2025). "Yet, our findings suggest PCSK9 inhibitors as potential risk factors for these cancers." (PMID 38275613, 2024). "However, further research is required to clarify the underlying mechanisms and clinical implications of PCSK9 in cancer biology." (PMID 39324018, 2024). "Besides, PCSK9 has been implicated in various diseases such as cancer biology and neurological disorders." (PMID 38344397, 2024).
cancer (continued). "In addition, PCSK9 expression strongly correlated with tumor-associated macrophages and DCs in these three cancers." (PMID 37860186, 2023). "Additionally, the increased PCSK9 levels were associated with a worse prognosis in many cancers; low levels of PCSK9 are connected to reduced tumour growth and improved prognosis." (PMID 37765005, 2023). "Therefore, cardioprotective properties of PCSK9 inhibitors should be urgently explored in randomized clinical trials in patients with cancer at high risk of ASCVD." (PMID 36900189, 2023). "The inhibition of PCSK9 caused apoptosis in cancer models in vitro." (PMID 37765005, 2023). "Furthermore, several experiments have demonstrated that PCSK9 is associated with cancers." (PMID 38344397, 2024). "Additionally, the knowledge gained from exploring the role of PCSK9 in cell proliferation and apoptosis could help to elucidate the potential involvement of this protein in cancer risk, providing insight into potential preventive strategies." (PMID 37860186, 2023). "Furthermore, whether the expression status of PCSK9 was associated with PFS in 38 cancer types was also investigated." (PMID 36545914, 2023). "This study reveals a novel lipid metabolism mechanism in cancer progression and positions PCSK9 as a promising therapeutic target for metastatic TNBC." (PMID 40192514, 2025). "Evolocumab is a clinically approved PCSK9 inhibitor which restores MHC-I expression in pre-clinical cancer models." (PMID 41131134, 2025). "Conversely, elevated PCSK9 levels shift cancer cells toward intrinsic cholesterol biosynthesis and antioxidant production, enhancing their survival in oxidative niches such as the lungs." (PMID 41008547, 2025). "Proprotein convertase subtilisin/kexin type 9 (PCSK9), widely known for regulating low-density lipoprotein (LDL) receptor turnover and systemic cholesterol levels, has recently been implicated in cancer biology." (PMID 41594607, 2025). "The broad cellular processes by which PCSK9 affects cancer progression are not limited to lipid regulation." (PMID 40354375, 2025). "Given that cancer is an age-related disease, PCSK9 has garnered attention for its potential impact on tumor progression and patient survival." (PMID 40576911, 2025). "Eliminating the PCSK9 gene in murine cancer cells markedly suppresses their proliferation in a way reliant on cytotoxic T lymphocytes." (PMID 40354375, 2025). "Our findings indicate a specific mechanism driving the abnormal elevation of PCSK9 expression in tumors through epigenetic regulation, which would provide a theoretical basis for targeting tumor PCSK9 expression in cancer immunotherapy." (PMID 40125618, 2025). "Taken together, these findings suggest a mechanistic rationale for evaluating PCSK9 inhibitors as cardioprotective agents in cancer therapy, forming the basis for the present study." (PMID 40724868, 2025). "The current work on PCSK9 is groundbreaking because it shifts the paradigm, demonstrating that inherited factors can influence the latter stages of cancer progression." (PMID 39872986, 2025). "PCSK9 inhibitors enhance the anti-cancer ICI therapy, e.g., PD-1 or PD-L1 blockage, via reduced LDL-C and TGF-β levels." (PMID 40563926, 2025). "In conclusion, several enzymes in the cholesterol biosynthesis pathway play a promotive role in cancer development, particularly SREBPs, HMGCR, and PCSK9, which are closely associated with the progression of HCC, CRC, and bc." (PMID 40145543, 2025). "Initially characterized for its role in cholesterol metabolism, PCSK9 is now recognized as a regulator of critical processes in cancer metastasis, including epithelial–mesenchymal transition (EMT), immune evasion, and endothelial activation." (PMID 40563628, 2025). "To elucidate the mechanisms through which PCSK9 promotes cell proliferation and cancer metastasis, we examined the levels of multiple oncogenic proteins by Western blot analysis." (PMID 40192514, 2025).